INCENP (inner centromere protein)
Description:
Component of the chromosomal passenger complex (CPC), a complex that acts as a key regulator of mitosis. The CPC complex has essential functions at the centromere in ensuring correct chromosome alignment and segregation and is required for chromatin-induced microtubule stabilization and spindle assembly. Acts as a scaffold regulating CPC localization and activity. The C-terminus associates with AURKB or AURKC, the N-terminus associated with BIRC5/survivin and CDCA8/borealin tethers the CPC to the inner centromere, and the microtubule binding activity within the central SAH domain directs AURKB/C toward substrates near microtubules. The flexibility of the SAH domain is proposed to allow AURKB/C to follow substrates on dynamic microtubules while ensuring CPC docking to static chromatin (By similarity). Activates AURKB and AURKC. Required for localization of CBX5 to mitotic centromeres. Controls the kinetochore localization of BUB1.
Synonyms: FLJ31633
Tractability: Small molecule: a structure with a bound ligand is known; a high-quality ligand is known. PROTAC: ubiquitination databases record sites on it; its protein half-life has been measured.
Target class: Other nuclear protein
Gene: Protein-coding gene on chromosome 11 (62,123,998 to 62,155,474, forward strand). Ensembl gene ENSG00000149503.
Subcellular location: Nucleus; Chromosome, centromere; Cytoplasm, cytoskeleton, spindle; Midbody; Chromosome, centromere, kinetochore
Subcellular location (Human Protein Atlas): Kinetochore; Nuclear bodies; Midbody; Nucleoplasm
Pathways (Reactome):
Cell Cycle: Amplification of signal from unattached kinetochores via a MAD2 inhibitory signal; EML4 and NUDC in mitotic spindle formation; Mitotic Prometaphase; Resolution of Sister Chromatid Cohesion; Separation of Sister Chromatids
Metabolism of proteins: SUMOylation of DNA replication proteins
Signal Transduction: RHO GTPases Activate Formins
Gene Ontology:
Molecular function: molecular function activator activity; protein binding
Biological process: chromosome segregation; mitotic cytokinesis; meiotic spindle midzone assembly; metaphase chromosome alignment; mitotic cell cycle; mitotic spindle assembly; mitotic spindle midzone assembly; positive regulation of attachment of mitotic spindle microtubules to kinetochore; positive regulation of mitotic cell cycle spindle assembly checkpoint; positive regulation of mitotic cytokinesis; positive regulation of mitotic sister chromatid separation
Cellular component: chromosome passenger complex; chromosome, centromeric region; kinetochore; microtubule cytoskeleton; midbody; nuclear body; nucleoplasm; nucleus; pericentric heterochromatin; protein-containing complex; spindle; cytosol; meiotic spindle midzone; chromosome
Genetic constraint (gnomAD): Loss-of-function variants: 43 observed, 102.83 expected, observed/expected ratio (o/e) 0.42, 90% interval 0.33 to 0.54. The upper end of that interval is the gene's LOEUF score, 0.54, which puts it in group 2 of 6, group 1 being the genes least tolerant of losing a copy. Missense variants: 1,082 observed, 1,268.6 expected, observed/expected ratio (o/e) 0.85, 90% interval 0.81 to 0.9. Synonymous variants: 487 observed, 501.44 expected, observed/expected ratio (o/e) 0.97, 90% interval 0.9 to 1.05.
Homologues: Orthologues: chimpanzee INCENP (99% identical), macaque INCENP (93% identical), rabbit INCENP (79% identical), dog INCENP (79% identical), pig INCENP (75% identical), guinea pig INCENP (70% identical), mouse Incenp (68% identical), rat Incenp (68% identical), tropical clawed frog incenp (45% identical).
Diseases named in the same sentence as INCENP in open-access papers:
INCENP is named in the same sentence as 22 diseases in open-access papers, as found by Europe PMC text mining. Sharing a sentence is not in itself a finding about the gene and the disease. The quoted sentences say what the papers report.
breast carcinoma (5 papers, 2018 to 2022). "For example, the inhibition of the protein INCENP (by the drug reversine) led to a reduction of migration potential of colon cancer cells and cell motility and invasion potential of breast cancer cells." (PMID 34680307, 2021). "To determine whether INCENP expression was increased in parallel with Aurora B expression, we analyzed breast cancer data from The Cancer Genome Atlas." (PMID 36313574, 2022). "However, INCENP expression does not correlate with Aurora B expression in human breast cancers, and increased Aurora B expression causes resistance rather than hypersensitivity to Aurora B inhibition." (PMID 36313574, 2022). "Co-expression of INCENP rescues Aurora B kinase activity and mitotic defects caused by elevated Aurora B. However, INCENP expression is not elevated in concert with Aurora B in breast cancer, and increased expression of Aurora B causes resistance rather than hypersensitivity to Aurora B inhibitors." (PMID 36313574, 2022). "To evaluate influence on PARP1 activity, we down-regulated the expression of RIT1, PSAT1 and INCENP by using siRNA and analyzed the level of PARylation in MCF7 breast cancer cell line." (PMID 31105872, 2019). "We decided to further validate RIT1, INCENP and PSTA1 in MCF7 breast cancer cells." (PMID 31105872, 2019). "However, since most breast cancers that overexpress Aurora B do not show similarly elevated levels of INCENP, these cancers are likely to have reduced, rather than elevated, levels of Aurora B kinase activity." (PMID 36313574, 2022).
neuroblastoma (4 papers, 2019 to 2023). Neuroblastoma (NB) is the most common solid, extracranial childhood tumor. "CPC disruption by targeting either INCENP or Survivin, whose expression correlates with high-risk disease in primary tumours, causes apoptosis in neuroblastoma cells, although at least for Survivin, it is unclear whether this is attributable to its part played in glycolytic metabolism." (PMID 37414143, 2023). "Of note, also silencing of INCENP induced polyploidization, apoptosis, and senescence in neuroblastoma cells, highlighting the importance of proper CPC localization for the prevention of senescence." (PMID 34100981, 2021). "INCENP depletion can suppress neuroblastoma cell growth by inducing polyploidization, apoptosis, and senescence." (PMID 33830865, 2021). "Furthermore, the combined inhibition of the direct identified targets such as CCND1, CHAF1A, INCENP and BCL-XL could reveal new vulnerabilities of high-risk neuroblastoma." (PMID 30770954, 2019).
colon cancer (3 papers, 2017 to 2023). "For example, SMYD3‐mediated AKT methylation at lysine 14 plays pivotal roles in activation of the AKT signaling pathway in breast and colon cancers, and PRMT1‐mediated methylation at arginine 887 of INCENP promotes mitosis of lung and cervical cancers." (PMID 28370702, 2017).
esophageal squamous cell carcinoma (3 papers, 2020 to 2025). Esophageal squamous cell carcinoma (ESCC) is a type of esophageal carcinoma (EC) that can affect any part of the esophagus, but is usually located in the upper or middle third. "For example, lncRNA MIAT can bind miR-1301-3p through “sponge” effect, and then form lncRNA MIAT/miR-1301-3p/INCENP regulatory pathway with the target gene INCENP of miR-1301-3p, which affects the progress of esophageal squamous cell carcinoma." (PMID 34460438, 2021). "Additionally, INCENP has been shown to be regulated by miR-1301–3p and contributes to the progression of esophageal squamous cell carcinoma." (PMID 40228435, 2025).
colorectal cancer (2 papers, 2015 to 2024). A primary or metastatic malignant neoplasm that affects the colon or rectum. "Overexpression of INCENP is observed in several colorectal cancer cell lines." (PMID 25923178, 2015).
bladder cancer (1 paper, 2015). "We here demonstrate that a protein arginine methyltransferase PRMT1, which are overexpressed in various types of cancer including lung and bladder cancer, methylates arginine 887 in an Aurora Kinase B (AURKB)-binding region of INCENP both in vitro and in vivo." (PMID 26460953, 2015).
breast tumors (1 paper, 2022). "This indicates that most breast tumors overexpressing Aurora B do not co-overexpress INCENP, strongly suggesting that these cancers have reduced, rather than elevated, Aurora B kinase activity." (PMID 36313574, 2022).
gastric cancer (1 paper, 2022). A primary or metastatic malignant neoplasm involving the stomach. "Similarly, using bioinformatics analysis, another concurrent study has shown that a G2/M checkpoint-related signature composed of five genes (MARCKS, CCNF, MAPK14, INCENP, and CHAF1A) was connected with the prognosis of gastric cancer (GC) patients." (PMID 35419294, 2022).
non-small cell lung carcinoma (1 paper, 2021). A group of at least three distinct histological types of lung cancer, including non-small cell squamous cell carcinoma, adenocarcinoma, and large cell carcinoma. "Moreover, PRMT1 can methylate the inner centromere protein (INCENP) at R887 to favor its interaction and the subsequent activation of aurora kinase B in A549 non-small cell lung cancer cells." (PMID 34833023, 2021).
prostate carcinoma (1 paper, 2019). A carcinoma that arises from epithelial cells of the prostate gland. "Interestingly, 9 out of 12 genes showed a medium expression correlation with PARP1 in prostate cancer; INCENP showed the highest correlation (p > 0.6)." (PMID 31105872, 2019).
cancer (16 papers, 2006 to 2025). A tumor composed of atypical neoplastic, often pleomorphic cells that invade other tissues. "INCENP contributes to susceptibility to ER-negative breast cancer in European populations, and the arginine methylation of INCENP is involved in mitosis in cancer cells." (PMID 40228435, 2025). "The CPC members, Survivin, Borealin, and INCENP, are present during interphase, and Survivin’s upregulation in cancer suggests a role beyond its mitotic functions." (PMID 39513910, 2024). "Previously, we have constructed a network of cancer stem cell genes, including INCENP, based on mRNA stemness indices (mRNAsi) of LUAD." (PMID 34621750, 2021). "INCENP can bind to the oncogenes survivin and borealin through its N-terminal domain (INCENP_N) form a trimer to exert its cancer-promoting function." (PMID 34621750, 2021). "By mapping ZDHHC5 correlated genes and mRNAsi-based cancer stemness genes, we identified INCENP, a stemness gene, as the bridge between ZDHHC5 and CSCs in LUAD." (PMID 34621750, 2021). "Particularly, the cell cycle and mitotic regulatory genes expression including: CDK2, CDK2AP2, ACTR3, and chromosome structure associated genes like SMC4, INCENP and GNL3L are changed in treated cancer cells." (PMID 30202240, 2018). "Knockdown of PRMT1 as well as overexpression of methylation-inactive INCENP attenuated the AURKB activity in cancer cells, and resulted in abnormal chromosomal alignment and segregation." (PMID 26460953, 2015). "The data indicate that INCENP methylation at R887 by PRMT1 is critical for the growth of cancer cells." (PMID 26460953, 2015). "We have demonstrated that the protein arginine methyltransferase PRMT1 methylates arginine 887 of INCENP, and that this methylation is critically important for the proper chromosomal segregation and cell division of cancer cells." (PMID 26460953, 2015). "Moreover, the phenotype of cancer cells after knockdown of PRMT1 is similar to that after knockdown of INCENP." (PMID 26460953, 2015). "In vitro, CDCA8, Survivin and INCENP were required for activation and/or localization of Aurora B. Our study and the previous studies suggested that Borealin could affect the growth and progression of cancer cells." (PMID 30142792, 2018). "Heatmap results showed that NRP1, MFAP2, KLC1, DST, and MYOZ3 were generally downregulated in cancer cell lines, while KIF21B, SRI, INCENP, and KEAP1 were also downregulated." (PMID 40228435, 2025). "Further validation in four independent cohorts showed that KEAP1, SRI, MFAP1, MFAP2, INCENP, and KIF21B were consistently upregulated in cancer tissues, while MYOZ3, DST, and TIAM1 were consistently downregulated." (PMID 40228435, 2025). "Survivin, together with INCENP, borealin, and AURKB to form CPC, has been reported to be overexpressed in many cancers and enable chemotherapy resistance." (PMID 35659274, 2022). "Recently it was reported that INCENP is mono-methylated on Arg887 by PRMT1, and that this promotes mitosis of cancer cells." (PMID 31320618, 2019). "Since our data revealed that PRMT1-mediated INCENP methylation is critical for the activation of AURKB, we then examined the effect of PRMT1 knockdown on the cell division of cancer cells." (PMID 26460953, 2015).
tumor (5 papers, 2007 to 2022). "Six genes were up-regulated in the tumor group and high-risk group consisting of SMAD3, CENPA, KIF23, NUSAP1, INCENP, and SMC4." (PMID 36401386, 2022). "Also, altered dosage and mis-localization of kinetochore proteins, such as CENP-A, CENP-H, Aurora-B and INCENP has been observed in various types of tumor cells." (PMID 21980305, 2011). "Also, altered dosage and mis-localization of kinetochore proteins, such as CENP-H, Aurora-B and INCENP has been observed in various types of tumor cells." (PMID 21980305, 2011).
infection (1 paper, 2014). The state of being infected such as from the introduction of a foreign agent such as serum, vaccine, antigenic substance or organism. "After depletion of INCENP, ANAPC, and AURKB, the time window was extended 3–5 fold resulting in a doubling or more in infection." (PMID 24874089, 2014). "To test whether prolongation of mitoses enhanced the probability of nuclear import (and infection), we depleted cells of mitotic regulators from the screen such as AURKB, INCENP, and ANAPC by RNAi to induce prolonged mitosis." (PMID 24874089, 2014).
INCENP also shares sentences with these, for which no sentence is quoted: glioma (2 papers); hepatocellular carcinoma (2); cervical cancer (1); Graham Little-Piccardi-Lassueur syndrome (1); lung carcinoma (1); malaria (1); prostate tumors (1); renal carcinoma (1); Roberts syndrome (1).